IL13 (interleukin 13)
Diseases named in the same sentence as IL13 in open-access papers (continued):
Sharing a sentence is not in itself a finding about the gene and the disease.
helminth infection (continued). "Besides that, adoptive transfer of Zeb1 KD cDC1 MutuDCs clears helminth infection by inducing IL-13 and IL-5 secreting Th2 cells in MLNs of infected animals." (PMID 30483264, 2018). "Helminth infection may activate adipocyte precursors to adopt a beige fate through induction of the cytokines IL-4/IL-13 and ILC2s9, as these Th2 promoting molecules and cells have been implicated in the commitment and maturation of beige adipocytes." (PMID 29545532, 2018). "ILC2-derived IL-5 is required for systemic maintenance of eosinophils and during type 2 inflammation ILC2s are induced to co-express IL-13, resulting in localized eotaxin production for recruitment and activation of eosinophils during allergic inflammation and helminth infection." (PMID 29163497, 2017). "In the process of M2 polarization and helminth infection, the immune response of the host to helminth infections is strikingly dominated by a Th2 response with a significant production of IL-4, IL-10, IL-13, and the STAT3/STAT6 signaling pathways have been detected." (PMID 28983296, 2017). "Helminth infections in human host cause an immune response associated with elevated levels of IgE, tissue eosinophilia and mastocytosis, and with the presence of CD4+ T cells that preferentially produce IL-4, IL-5, and IL-13." (PMID 27980457, 2016). "Indeed it has been shown that ILC2s, in particular, provide an early source of IL-13 during experimental helminth infection." (PMID 25799270, 2015). "However, IL-5 and IL-13 cytokine responses to Ascaris worm challenge were detectable in all subgroups with evidence of helminth infection (eggs or high IgE)." (PMID 25209883, 2014). "Eosinophils are a rapid source of IL-4 and IL-13 cytokines during helminth infection." (PMID 25028340, 2014). "Although IL-10 was associated with helminth infections, this association was not significant after adjustment for confounders; and IL-13 production was significantly associated only with having three helminth infections." (PMID 25410903, 2014). "Studies in mice have shown that the helminth induced increase in smooth muscle contractility is signaled through IL4 or IL-13, which could explain why it is a common observation with helminth infections." (PMID 24340121, 2013). "IL-4 and IL-13 are induced by injury or helminth infections." (PMID 24124601, 2013). "Our data suggest that IL-25 is essential for type-2 cytokine production by mesenteric lymph node (MLN) cells, as well as being essential for IL-13 production by leukocytes in the intestinal mucosa; this result supports previous findings in helminth infection and in lung inflammation." (PMID 22539101, 2012). "In another mucosal context, the intestine, IL-25 has been described to play a role in the protection against helminth infection by inducing a strong type-2 innate inflammation which is dependent upon the activation of IL-17BR+ nuocytes and their production of IL-13." (PMID 22539101, 2012). "However, similar to the ability of IL-4 and IL-13 to induce the alternatively activated phenotype in macrophages in the context of helminth infections, fungus-induced Arg1 was also found to be at least partially dependent on IL-4Rα/STAT6." (PMID 21246055, 2011). "In addition to promoting goblet cell responses during helminth infection, ILC2s derived IL-13 may also play a supportive role in shaping the mucosal cytokine environment during bacterial infection." (PMID 40591723, 2025). "In general, helminth infections develop a Th2-type immune response with an increase in IL-4, IL-5, IL-13 and IL-33 cytokines, which may assist in the expulsion of worms in the lungs, but there are still no studies on the importance of the cytokine IL-33 in T. canis infection." (PMID 34324507, 2021). "GCs proliferation caused by helminth infection is mainly controlled by IL-4 and IL-13 in the Th2 immune response, but the GCs proliferation caused by Syphacia obvelata and Schistosoma mansoni infection is independent of IL-4 and IL-13." (PMID 33017020, 2020).
helminth infection (continued). "Furthermore, helminth infection promotes the early recruitment of the phagocytes Eos, mast cells, and basophils at the site of infections, which provide the rapid secretion of the Th2-type cytokines IL-4, IL-13, and TSLP." (PMID 29670630, 2018). "Interestingly, IL-13, a gene associated with fibrosis and Th2 responses in other helminth infections, also increased in EB-stained capsules, but not in clear capsules, at 120 hr post treatment." (PMID 25774662, 2015). "Validating our expectations, for these cytokines and other T helper Th-2 cytokineslike IL-13 and IL-4, their DDI statuses were lost after treatment for helminth infection." (PMID 41174472, 2025). "During intestinal helminth infection, immune cells—particularly ILC2—secrete abundant interleukin-13 (IL-13)." (PMID 40356895, 2025). "Another source of IL-4, essential to generating M2 macrophages during helminth infections, is the T-CD4+ lymphocyte, where the synergy between T cells and group 2 innate lymphoid cells (ILC2) for IL-13 production has been described." (PMID 38392907, 2024). "During helminth infection in the lung and intestine, ILC2s produced IL4 and IL13 using a BATF-dependent mechanism in response to epithelial damage and contributed to the epithelial restoration." (PMID 37893107, 2023). "During helminth infections, another AP-1 family molecule, basic leucine zipper ATF-like transcription factor (BATF), induces IL-4 and IL-13 in ILC2s32." (PMID 36109558, 2022). "It is known that IL-4/IL-13-mediated STAT6 signaling plays a central role in promoting tuft and goblet cell hyperplasia in the small intestine during helminth infection." (PMID 36232438, 2022). "Our results show that Gpr44−/− mice have decreased proliferation in vivo following helminth infection and that PGD2 via CRTH2 counteracts IL-13–mediated repression of IEC proliferation in vitro." (PMID 34283207, 2021). "Intravital imaging demonstrated an increase in IL-13+ ILC2 size and movement following helminth infection, but reduced duration of interactions with T cells compared with those in homeostasis." (PMID 34484215, 2021). "EGFR expression on Th2 cells is critical for resistance during GI helminth infection and a signalling complex between EGFR and ST2 can activate Th2 cells to secrete IL-13 in an antigen-dependent manner upon IL-33 exposure." (PMID 32636457, 2020). "A precise understanding of the molecular signaling mechanisms suggests that targeting IL-13, while equally effective, preserves IL-4 signaling through the type-2 IL-4 receptor which may constitute an important safety benefit regarding immunity, especially to helminth infections." (PMID 30759882, 2019). "After helminthic infection and in response to IL33, FALC Lin−c-Kit+Sca-1+ cells produce large amounts of IL13, which leads to goblet cell hyperplasia and contribute to the expulsion of helminthes." (PMID 29081776, 2017). "IL-5 and IL-13, produced by ILC2, can recruit eosinophils which are essential for the clearance of helminth infections." (PMID 29354125, 2017). "The ligands of the IL13Rα1, IL13 and IL4, are components of type II immune responses, which characterize allergic reactions and helminth infections, and, interestingly, are also involved in the susceptibility of DA neurons to death by oxidative stress." (PMID 25525298, 2014). "In helminth infection, macrophages are activated into different inflammatory states, including classically activated macrophages (M1) induced by lipopolysaccharide (LPS) and IFN-γ and alternatively activated macrophages (M2) induced by IL-4 and IL-13." (PMID 37705099, 2023). "Thus, helminth infection attenuated the Th17 response to MINCLE-dependent immunization in an organ- and adjuvant-specific manner via the Th2 cytokines IL-4/IL-13." (PMID 36753434, 2023). "Helminth infection and Type 2 cytokines (specifically IL-13) both regulate IEC functions, but the effects of helminth infection are not precisely the same as those of IL-13." (PMID 34283207, 2021).
helminth infection (continued). "It was later shown that innate lymphoid cells could respond to the tissue alarmin TSLP to produce IL-5 and IL-13, but this appears to occur mainly in the skin leaving the impact of TSLP in other stages of helminth infection less clear." (PMID 32793230, 2020). "Yet, the deletion of Arg-1 affected neither lung ILC2 proliferation nor expression of cytokines IL-5 and IL-13 after helminth infection." (PMID 29762526, 2018). "In conclusion, during a helminth infection that strongly polarizes the macrophages towards M(IL-4/IL-13), the lack of E-cadherin in these cells is not sufficient to alter their activation state and to have an impact on the outcome of the disease." (PMID 26226941, 2015). "IL-13 and/or IL-4, which both use the IL-4Rα chain, are also central to resistance against many if not most helminth infections." (PMID 25028340, 2014). "IL-4 and IL-13 were shown previously to induce the expression of macrophage IGF-1 and coincident expression of type 2 cytokines and IGF-1 was demonstrated in experimental helminth infection." (PMID 24967908, 2014). "Maternal Mansonella perstans infection was associated with higher interleukin (IL)-10 responses to both immunogens but no reduction in gamma interferon (IFN-γ), IL-5 and IL-13 responses; other maternal helminth infections showed little effect." (PMID 21040693, 2010). "IL-13, a prototype Th2 cytokine, is a major inducer of fibrosis in many chronic infectious and autoimmune diseases, while TNF has been shown to be a critical component of the IL-13 mediated protective Th2 response during helminth infection." (PMID 17205112, 2006). "In addition, T cells have previously been shown to work with ILC2s in the clearance of helminth infections, where mice that lacked IL13 producing T cells had a reduced ILC2 response and helminth clearance." (PMID 37898600, 2023). "However, because IL-4R-independent AAMφ differentiation has also been demonstrated in helminth infections, we examined Mφ development in either Severe-combined (SCID; no functional T or B cells) or IL-4Rα deficient (IL-4/IL-13 non-responsive) BALB/c mice." (PMID 29547639, 2018). "It is corroborated that Th2 immune responses which are responsible for the resistance of hosts to the helminthic infection could activate TGF-β1 via producing IL-4 and IL-13 and TGF-β signaling pathway, and the latter in turn acts as a prominent mediator in fibrosis." (PMID 28151995, 2017). "Finally, although CD4+ TRM cells can produce IFNγ/IL-17, and IL-4/IL-13 following helminth infection, their production of IL-10 has not previously been reported." (PMID 25974019, 2015). "Furthermore, IL-4 as well as IL-13 could potently induce liver fibrosis which inhibited liver injuries due to accumulated Th1 like responses (such as TNF-α and IFN-γ) at the early stages of helminthic infection." (PMID 33489026, 2020). "Our results demonstrate for the first time that intestinal goblet cell hyperplasia in response to parasitic helminth infections can occur independently of IL-4/IL-13 signalling and that intestinal nematode infections may not always induce a goblet cell response." (PMID 18373844, 2008). "In a helminth infection model, mice lacking CCR8 exhibit reduced type 2 cytokines IL-5, IL-13, and IL-9, and greater worm burden in the small intestine." (PMID 35707544, 2022). "To confirm whether type 2 cytokines IL-4, IL-5, IL-9, and IL-13 contributed to helminth-induced protection against TNF-α and IFN-γ shock, we compared the levels of cytokines in the presence or absence of the helminth infection." (PMID 38727220, 2024). "Notably, IL-13 response by ILC2 was diminished when transferred without OTII T cells, highlighting the interdependency of ILC2 and CD4+ T cell in responding to helminth infections." (PMID 35145516, 2022).
airway hyperresponsiveness (187 papers, 2008 to 2026). "RV infection of 6 day-old mice, but not mature mice, induces type airway inflammation, mucous metaplasia and airways hyperresponsiveness which is associated with expansion of IL-13-producing ILC2s and dependent on the innate cytokines IL-25, IL-33 and TSLP." (PMID 41573550, 2025). "We demonstrate that camel milk suppresses airway hyperresponsiveness, Th2 and Th17 cell recruitment, and associated cytokines (IL-4, IL-5, IL-13, IL-17A), while reducing dendritic cell activity and CCL17 expression in the lungs." (PMID 40577410, 2025). "IL-13 is a pleiotropic cytokine that causes goblet cell hyperplasia and excessive mucus production in vitro, as well as airway hyperresponsiveness, allergic inflammation, and tissue remodeling in vivo." (PMID 39440037, 2024). "Of those dysregulated genes, four were associated with immune-mediated inflammatory diseases (Csf2; Crlf2; Rnase2b; Tpsb2) and one with airway hyperresponsiveness (Prg2), while Il-13 was associated with both of those pathways." (PMID 36834405, 2023). "IL13 has been implicated in development and expression of airway hyperresponsiveness, with IL13 alone shown to be sufficient to induce responses in murine models." (PMID 33918602, 2021). "As a result, Th2 cells increase in T-bet-deficient mice and spontaneously help to form airway hyperresponsiveness associated with overproduction of Th2 cytokines (IL-4, IL-5 and IL-13) and to cause infiltration of eosinophils and lymphocytes." (PMID 32489402, 2020). "The combination of IL-6 and IL-8 is frequently used in ARDS research, whereas IL-13 was only present in combination with high IL-5 concentrations; both are T-helper cell 2 cytokines associated with airway hyperresponsiveness." (PMID 31998415, 2020). "Type 2 cytokines such as IL-4, IL-5, and IL-13 cause airway hyperresponsiveness, mucus secretion, and eosinophil aggregation and induce B lymphocyte to produce IgE-mediated allergic reaction." (PMID 31737687, 2019). "In SP‐D‐deficient OVA‐challenged mice, airway hyperresponsiveness was significantly enhanced despite the lower eosinophil count and the concentration of interleukin (IL)‐5 and IL‐13 in BALF compared with WT OVA‐challenged mice at 120 ventilations per minute." (PMID 29368450, 2018). "In conclusion, we show here in this study that March1 E3 ubiquitin ligase contributes to the development of allergic inflammatory response by promoting Th2 cytokines, particularly those implicated in IgE class switching and airway hyperresponsiveness (IL-13)." (PMID 29854835, 2018). "IL-13 is a pleiotropic cytokine produced mainly by T cells and is critical for the development of airway hyperresponsiveness (AHR) associated with allergen exposure." (PMID 24723965, 2014). "Interleukin-13 is implicated as a central regulator in IgE synthesis, mucus hypersecretion, airway hyperresponsiveness, and fibrosis." (PMID 23283176, 2011). "RV infection of 6 day-old mice, but not mature mice, induces type 2 airway inflammation, mucous metaplasia and airways hyperresponsiveness which is associated with expansion of IL-13-producing type 2 innate lymphoid cells (ILC2s) and dependent on the innate cytokines IL-25, IL-33 and TSLP." (PMID 41573550, 2025). "The allergic form is an adaptive T helper 2-driven disease characterized by elevated levels of interleukin (IL)-5, interleukin-4 (IL-4), and IL-13, associated with enhanced levels of circulating and lung eosinophils, elevated serum IgE, mucus hypersecretion and airway hyperresponsiveness." (PMID 34744763, 2021). "IL-13 is associated with eosinophilic lung inflammation, airway epithelial cell hypertrophy, goblet cell metaplasia, mucus hypersecretion, subepithelial fibrosis, and airway hyperresponsiveness." (PMID 34930201, 2021).
airway hyperresponsiveness (continued). "It has been suggested that TSLP is responsible for the activation and expansion of this IL-13-producing subset, since TSLPR KO mice exhibited diminished weight loss, lower levels of IL-13-producing ILC2s, lower lung IL-13 levels, and lower airway hyperresponsiveness (AHR) compared to WT mice." (PMID 32545470, 2020). "It has also been suggested that IL-13 is involved in mucus metaplasia that can increase susceptibility to rhinovirus and decreasing IL-13 levels can reduce mucus production, airway hyperresponsiveness and partly reduce airway eosinophilia during rhinoviral infection." (PMID 30759882, 2019). "IL-4, IL-5, IL-6, and IL-13 have been shown to maintain this cycle of allergic inflammation with IL-4 promoting Ig isotype switching, IL-5 inducing eosinophil differentiation and migration, and IL-13 causing goblet cell hyperplasia and airway hyperresponsiveness." (PMID 30380761, 2018). "TET1 negatively regulates allergic airway inflammation by suppressing the expression of pro-inflammatory and epithelial genes such as Il13, Il33, Il17a, Muc5ac, Egfr, and Tff2, thereby limiting airway hyperresponsiveness." (PMID 41008562, 2025). "In SA, epithelial-derived cytokines play a central role in initiating and sustaining type 2 (T2) inflammation by activating the IL-4, IL-5, and IL-13 axis, leading to increased eosinophils, elevated serum IgE, and heightened airway hyperresponsiveness." (PMID 41169790, 2025). "In our investigation, the choice of indicators, including airway hyperresponsiveness, cytokine concentrations (IL-4, IL-5, and IL-13), IgE titers, and histopathological examinations, was pivotal for evaluating the efficacy of hydrogen therapy." (PMID 41146240, 2025). "IL-13 is essential in excessive mucus secretion, immune cell influx, and airway hyperresponsiveness." (PMID 40709340, 2025). "IL-13 has an impact on increased secretion of IgE, increased production of NO (induction of iNOS expression), airway hyperresponsiveness (increased expression of FcεRI) and fibroblasts proliferation (activation of TGF-β1)." (PMID 40389545, 2025). "IL-13 promotes airway hyperresponsiveness by inducing the contraction of airway smooth muscle cells and stimulating mucus secretion from epithelial cells hallmark features of allergic asthma." (PMID 41008562, 2025). "While IL‐13 is known to induce tissue remodeling, airway hyperresponsiveness, and mucus secretion in the lung, IL‐5 is a key stimulus for the recruitment and survival of eosinophils." (PMID 39955650, 2025). "At the same time, IL-13 induces airway hyperresponsiveness (AHR), stimulates goblet cells, and increases mucus secretion." (PMID 40558541, 2025). "IL-4 and IL-5 regulate the maturation and release of eosinophils in the bone marrow, while IL-13 promotes B cell differentiation and plays a leading role in airway inflammation, airway hyperresponsiveness, and mucus secretion." (PMID 40070820, 2025). "IL-13 is produced by activated airway hyperresponsiveness (AHR)-related cells including Th2 cells, which can thicken the airway wall by promoting goblet cell proliferation and mucus secretion." (PMID 40953067, 2025). "Previous research has shown that the overexpression of IL-13 in transgenic mice leads to enhanced eosinophilic inflammation and airway hyperresponsiveness, as well as increased proportions of Proteobacteria and Cyanobacteria in the lungs." (PMID 38397126, 2024). "We have shown that RV1B infection of 6-day-old mice induces mucous metaplasia and airway hyperresponsiveness that is associated with ILC2 expansion and dependent on IL-13, IL-25, IL-33, and TSLP." (PMID 38061015, 2024). "I.n. challenge of sensitized animals led to increased BAL type 2 cytokines (IL-4, IL-5 and IL-13) as well as airway hyperresponsiveness." (PMID 39157265, 2024).